SYT11 (synaptotagmin 11)
Description:
Synaptotagmin family member involved in vesicular and membrane trafficking which does not bind Ca(2+). Inhibits clathrin-mediated and bulk endocytosis, functions to ensure precision in vesicle retrieval. Plays an important role in dopamine transmission by regulating endocytosis and the vesicle-recycling process. Essential component of a neuronal vesicular trafficking pathway that differs from the synaptic vesicle trafficking pathway but is crucial for development and synaptic plasticity. In macrophages and microglia, inhibits the conventional cytokine secretion, of at least IL6 and TNF, and phagocytosis. In astrocytes, regulates lysosome exocytosis, mechanism required for the repair of injured astrocyte cell membrane (By similarity). Required for the ATP13A2-mediated regulation of the autophagy-lysosome pathway.
Synonyms: SytXI; KIAA0080; MGC10881; MGC17226; DKFZp781D015
Tractability: Antibody: UniProt predicts a signal peptide or a membrane-spanning region; its Gene Ontology location is reachable by antibodies, with medium confidence. PROTAC: UniProt records ubiquitination sites on it; ubiquitination databases record sites on it.
Gene: Protein-coding gene on chromosome 1 (155,859,449 to 155,885,199, forward strand). Ensembl gene ENSG00000132718.
Subcellular location: Cytoplasmic vesicle membrane; Perikaryon; Golgi apparatus, trans-Golgi network membrane; Recycling endosome membrane; Lysosome membrane; Cytoplasmic vesicle, phagosome; Cell projection, axon; Cell projection, dendrite; Postsynaptic density; Cytoplasmic vesicle, clathrin-coated vesicle membrane
Pathways (Reactome):
Vesicle-mediated transport: Cargo recognition for clathrin-mediated endocytosis; Clathrin-mediated endocytosis
Gene Ontology:
Molecular function: protein binding; ubiquitin protein ligase binding; calcium ion binding; calcium ion sensor activity; calcium-dependent phospholipid binding; identical protein binding; SNARE binding; beta-tubulin binding; translation initiation factor binding
Biological process: autophagy; calcium ion regulated lysosome exocytosis; calcium-dependent activation of synaptic vesicle fusion; establishment of vesicle localization; learning; memory; negative regulation of cytokine production; negative regulation of dopamine secretion; negative regulation of endocytosis; negative regulation of interleukin-6 production; negative regulation of microglial cell activation; negative regulation of neurotransmitter secretion; negative regulation of phagocytosis; negative regulation of tumor necrosis factor production; plasma membrane repair; positive regulation of protein localization to phagocytic vesicle; regulation of calcium ion-dependent exocytosis; regulation of phagosome maturation; vesicle fusion; vesicle-mediated transport; negative regulation of secretion by cell; regulation of defense response to bacterium; regulation of synaptic vesicle endocytosis; response to wounding
Cellular component: neuron projection; perikaryon; axon; dendrite; dendritic spine; early phagosome; excitatory synapse; exocytic vesicle; inhibitory synapse; lysosomal membrane; lysosome; phagocytic vesicle; plasma membrane; postsynaptic density; presynapse; presynaptic active zone membrane; recycling endosome; recycling endosome membrane; synapse; synaptic vesicle; trans-Golgi network; vesicle; clathrin-coated vesicle membrane; cytoplasm; cytoplasmic vesicle membrane; and 4 more
Genetic constraint (gnomAD): Loss-of-function variants: 8 observed, 27.73 expected, observed/expected ratio (o/e) 0.29, 90% interval 0.17 to 0.52. The upper end of that interval is the gene's LOEUF score, 0.52, which puts it in group 2 of 6, group 1 being the genes least tolerant of losing a copy. Missense variants: 372 observed, 532.02 expected, observed/expected ratio (o/e) 0.7, 90% interval 0.64 to 0.76. Synonymous variants: 185 observed, 205 expected, observed/expected ratio (o/e) 0.9, 90% interval 0.8 to 1.02.
Homologues: Orthologues: chimpanzee SYT11 (99% identical), macaque SYT11 (99% identical), guinea pig SYT11 (98% identical), mouse Syt11 (95% identical), pig SYT11 (95% identical), rabbit SYT11 (95% identical), dog SYT11 (94% identical), rat Syt11 (93% identical), zebrafish syt11a (66% identical), zebrafish syt11b (62% identical), tropical clawed frog syt11 (55% identical). Paralogues in human: SYT4 (52% identical), SYT7 (38% identical), SYT6 (34% identical), SYT10 (34% identical), SYT1 (31% identical), SYT3 (31% identical), SYT5 (31% identical), SYT9 (31% identical), SYT2 (30% identical), SYT17 (27% identical), RPH3A (25% identical), SYT8 (24% identical), and 19 more.
Diseases named in the same sentence as SYT11 in open-access papers:
SYT11 is named in the same sentence as 49 diseases in open-access papers, as found by Europe PMC text mining. Sharing a sentence is not in itself a finding about the gene and the disease. The quoted sentences say what the papers report.
Parkinson disease (14 papers, 2012 to 2026). A progressive degenerative disorder of the central nervous system characterized by loss of dopamine producing neurons in the substantia nigra and the presence of Lewy bodies in the substantia nigra and locus coeruleus. "SYT11 is a non-Ca2+ binding protein associated with schizophrenia and Parkinson’s disease, which is mainly involved in vesicle fusion, transport, and exocytosis." (PMID 35205089, 2022). "Syt11 is genetically linked to risk of Parkinson’s disease and it is a substrate of PRKN (encoded by PARK2), an E3 ubiquitin ligase that is often mutated in familial cases of Parkinson’s disease." (PMID 34702310, 2021). "A meta-analysis of genome-wide association studies showed that a common variant at the SYT11/RAB25 locus is associated with Parkinson's disease in Caucasians17, suggesting a role for this gene in neurodegenerative diseases." (PMID 25773295, 2015). "Synaptotagmin 11 (Syt11), a substrate for ubiquitinylation by parkin, is one of the risk genes for Parkinson's disease; overexpression (resulting from parkin dysfunction) leads to impaired dopamine release, degeneration of dopaminergic neurons, and associated motor behavioral deficits." (PMID 32292341, 2020). "Eight loci-PRKN, SNCA, GBA1, LRRK2, APOE, MTHFR, SYT11, and NR4A2-emerged as recurrently associated with Parkinson's disease." (PMID 41798285, 2026). "The role of palmitoylation in a pathological context has been shown in Parkinson’s disease, with the accumulation of α-synuclein as a downstream effect of the palmitoylation of vesicle-trafficking protein Synaptotagmin-11 (Syt11)." (PMID 39483499, 2024). "Currently, studies of the SYT11 gene mainly focus on neurological diseases such as schizophrenia and Parkinson’s disease." (PMID 35205089, 2022). "Furthermore, a previous study showed that synaptotagmin-11 plays a role in Parkin-related parkinsonism." (PMID 38295113, 2024). "Several of these have been associated with other neurodegenerative disorders (ZDHHC17 with Huntington’s disease, SYT11 and GAK with Parkinson’s disease and GABRB3 with dementia with Lewy bodies), and may be of special interest for future studies." (PMID 34202490, 2021).
schizophrenia (8 papers, 2014 to 2025). A major psychotic disorder characterized by abnormalities in the perception or expression of reality. "SYT11 is a member of the synaptotagmin family, which is associated with susceptibility to Parkinson’s disease (PD) and schizophrenia." (PMID 40755781, 2025). "A few studies have associated SYT11 with schizophrenia and Parkinson’s disease (PD), and SYT11 can accumulate in dopaminergic neurons lacking Parkin." (PMID 33619613, 2021). "Although the role of SYT11 in neural function is not well understood, there is evidence that there is a relationship between expression of SYT11 and the development of schizophrenia." (PMID 25393317, 2014). "SYT11, which regulates immune functions, neurotoxicity, and synaptic plasticity, has been reported in various neurological disorders, including AD, PD, and schizophrenia." (PMID 40631452, 2025). "The study analysing gene-miRNA interaction network identified miRNAs (miR-92a, miR-495, miR-134) directly regulating gene expression by the binding site in BCL11 A, PLP1 and SYT11, which are changed in the PFC in patients with schizophrenia." (PMID 36833173, 2023).
gastric cancer (4 papers, 2022 to 2025). A primary or metastatic malignant neoplasm involving the stomach. "SYT11 is a highly expressed gene in the stem‐like molecule subtype of gastric cancer and is associated with poor prognosis." (PMID 40576306, 2025). "Similarly, the reduction in gastric cancer cell invasion caused by VHL was restored by the overexpression of SYT11 and SPINK1." (PMID 40576306, 2025). "In addition, it is upregulated with SYT11 expression, associated with the stem-like molecular subtype of gastric cancer, and a prognostic biomarker for histologically classified diffuse-type gastric cancer." (PMID 38890718, 2024). "The present study demonstrates that VHL inhibits gastric cancer cell proliferation and invasion by promoting proteasome‐dependent degradation of SYT11, thereby downregulating SPINK1." (PMID 40576306, 2025). "VHL and SYT11 contribute to gastric cancer progression via distinct pathways, but both are involved in the ubiquitin–proteasome system, suggesting possible convergence in post‐translational control." (PMID 40576306, 2025). "Analyses of public data confirmed that high expression of VHL and low expression of SYT11 are positively correlated with improved prognosis of gastric cancer patients." (PMID 40576306, 2025). "In our previous study, SYT11 was found to promote gastric cancer development through the MAP kinase (MKK7)‐c‐Jun N‐terminal kinases (JNK) pathway." (PMID 40576306, 2025). "Consistent with previous studies, SYT11 expression in gastric cancer cell line MKN1 was downregulated by Parkin." (PMID 40576306, 2025). "The VHL‐induced reduction in gastric cancer cell growth and invasion was rescued by overexpression of SYT11 and SPINK1." (PMID 40576306, 2025). "Next, we investigated the effect of VHL on SYT11 expression in gastric cancer cells." (PMID 40576306, 2025). "Additionally, it will be important to investigate the combined effects of HIF‐1α, a VHL target, and SYT11 on the growth, migration, and invasion of gastric cancer cells following VHL inhibition." (PMID 40576306, 2025). "These analyses suggest that VHL may inhibit gastric cancer cell growth by suppressing SYT11 protein expression." (PMID 40576306, 2025). "In SYT11‐transfected gastric cancer cells, VHL reduced SYT11 protein expression and its half‐life." (PMID 40576306, 2025). "VHL expression is negatively correlated with SYT11 expression in gastric cancer patients." (PMID 40576306, 2025). "This study investigates whether von Hippel–Lindau (VHL), an E3 ligase, regulates the stability of synaptotagmin 11 (SYT11) protein in gastric cancer cells." (PMID 40576306, 2025). "In this study, we have uncovered a novel mechanism by which VHL decreases SYT11 protein stability, thereby downregulating SPINK1 expression and inhibiting the growth and invasion of gastric cancer cells." (PMID 40576306, 2025). "Given the low expression of Parkin and high expression of VHL in gastric cancer cell lines, we investigated the role of VHL in regulating SYT11 expression." (PMID 40576306, 2025). "Finally, we evaluated the role of SYT11 and SPINK1 in VHL‐mediated inhibition of gastric cancer cell growth." (PMID 40576306, 2025). "Although SYT11 expression does not perfectly align with survival prognosis, no reported studies have focused on tumors other than some lung and gastric cancers; therefore, the differential SYT11 expression is considered to be closely related to the survival prognosis of most tumors in this study." (PMID 38890718, 2024).
lung carcinoma (3 papers, 2024 to 2025). "Our functional experiments inhibiting these genes showed that loss of Ptgds, Arl2bp, Rnf157, and Syt11 can block lung cancer sphere formation." (PMID 40047406, 2025). "A recent study revealed that SYT11 driven the invasion and metastasis of lung cancer by altering the tumor microenvironment." (PMID 38526709, 2025).
acute myeloid leukemia (2 papers, 2024 to 2025). Acute myeloid leukemia (AML) is a group of neoplasms arising from precursor cells committed to the myeloid cell-line differentiation. "Notably, high SYT11 expression in other cancer types, such as Adrenocortical Cancer, Bladder Cancer, Acute Myeloid Leukemia, Mesothelioma, and Ocular Melanomas, also associated with poor prognoses." (PMID 38526709, 2025).
cognitive decline (2 papers, 2021). "In mice, Syt11 deficiency in excitatory glutamatergic neurons impairs synaptic plasticity and memory, thereby suggesting that Syt11 dysregulation contributes to AD-associated cognitive decline." (PMID 34702310, 2021).
Parkinsonism (2 papers, 2022 to 2024). Characteristic neurologic anomaly resulting from degeneration of dopamine-generating cells in the substantia nigra, a region of the midbrain, characterized clinically by shaking, rigidity, slowness of movement and difficulty with walking and gait. "In particular, we envisage that more detailed investigations on experimental models of GBA1-, SYNJ1-, SYPH1-, TMEM230-, Parkin-, PINK1-, ATP13A2-, FBXO7- and SYT11-associated parkinsonism could provide new insight into the pathophysiological mechanisms leading to PD that may involve Rab dysfunction." (PMID 36009486, 2022).
amyloid (1 paper, 2021). "Importantly, we found that Syt11 co-localized with Aβ plaques in AppNL-G-F mice, thereby suggesting that accumulation of Syt11 in amyloid plaques contributes to the AD pathology." (PMID 34702310, 2021).
atrial fibrillation (1 paper, 2024). A disorder characterized by an electrocardiographic finding of a supraventricular arrhythmia characterized by the replacement of consistent P waves by rapid oscillations or fibrillatory waves that vary in size, shape and timing and are accompanied by an irregular ventricular response. "There is no information to date about the role of Usp31 in cardiac pathophysiology, but Syt11 was reported to decrease the risk of atrial fibrillation." (PMID 38534766, 2024). "Of all 19,605 quantified genes, the largest increase in ΔREC in LSD was exhibited by Usp31 (ΔREC = 2411%), a potential biomarker for clear cell renal cell carcinoma and Syt11 (ΔREC = 1517%), known for its role in atrial fibrillation." (PMID 38534766, 2024).
breast carcinoma (1 paper, 2023). "We were able to confirm the data obtained in the model TAMs it tumor samples of patients with breast cancer, and found enhancing effects of cisplatin on SYT11 expression." (PMID 36960065, 2023). "Cisplatin suppressed both overall and EGF-specific endocytosis in TAMs by bidirectional mode: suppression of positive regulators and stimulation of negative regulators of endocytosis, with strongest effect on synaptotagmin-11 (SYT11), confirmed in patients with breast cancer." (PMID 36960065, 2023).
diabetic retinopathy (1 paper, 2020). "Moreover, SP1 regulates the expression of the RGC‐specific gene syt11,42 and its expression is upregulated in the RGCs of patients with diabetic retinopathy." (PMID 32562344, 2020).
glioblastoma (1 paper, 2020). The most malignant astrocytic tumor (WHO grade IV). "It would be interesting to test the idea that Syt11 in glioblastoma slows endocytosis of GluA2 receptors, promoting glutamate-driven signaling." (PMID 32292341, 2020). "Very high transcript levels in glioblastoma were measured for synaptotagmin-11." (PMID 32292341, 2020).
kidney cancer (1 paper, 2024). Primary or metastatic malignant neoplasm involving the kidney. "In parallel with these findings, SYT11 mRNA levels were negatively correlated with miR-19a-3p levels in lung and kidney cancer cell lines (r = − 0.2537; p = 0.0331)." (PMID 38890718, 2024).
melanoma (1 paper, 2022). A malignant, usually aggressive tumor composed of atypical, neoplastic melanocytes. "After 18 days of transplanting the mouse melanoma B16F10-Luc cells into the mouse tail vein, increased lung metastasis was observed in SYT11-Tg mice compared with WT mice." (PMID 35768842, 2022).
microcephaly, primary autosomal recessive 1 (1 paper, 2024). "Mcph1 (microcephaly, primary autosomal recessive 1; REC-N = 39.05) was the most controlled gene in “N”, while Usp31 (ubiquitin specific peptidase 31, REC-L = 27.93) and Syt11 (synaptotagmin XI, REC-L = 26.25) were the most controlled genes in “L”." (PMID 38534766, 2024).
pheochromocytoma (1 paper, 2025). "Then, we constructed amino acid metabolism profiles by WGCNA and LASSO regression model for investigating the impact of amino acid metabolism on pheochromocytoma pathogenesis and immunity and identified six hub genes (DDC, SYT11, GCLM, PSMB7, TYRO3, and AGMAT)." (PMID 38526709, 2025).
renal carcinoma (1 paper, 2024). A carcinoma arising from the epithelium of the renal parenchyma or the renal pelvis. "In vitro experiments further verified a negative correlation between the expression of SYT11 and miR-19a-3p in human colorectal, lung, and renal cancer cell lines." (PMID 38890718, 2024).